OR2C1 (olfactory receptor family 2 subfamily C member 1)
Description:
Olfactory receptor that is activated by the binding of organosulfur odorants with thioether groups such as (methylthio)methanetiol (MTMT) (By similarity). Also binds odorants acetophenone and benzaldehyde (By similarity). The activity of this receptor is mediated by G proteins which activate adenylyl cyclase (By similarity). May be involved in the molecular processes underlying fasciculation and targeting of olfactory axons (By similarity).
Synonyms: OR2C2P; OLFmf3
Tractability: Antibody: its Gene Ontology location is reachable by antibodies, with high confidence; UniProt places it where antibodies can reach, with medium confidence; UniProt predicts a signal peptide or a membrane-spanning region. PROTAC: ubiquitination databases record sites on it.
Gene: Protein-coding gene on chromosome 16 (3,355,889 to 3,357,306, forward strand). Ensembl gene ENSG00000168158.
Subcellular location: Cell membrane
Pathways (Reactome):
Sensory Perception: Expression and translocation of olfactory receptors; Olfactory Signaling Pathway
Gene Ontology:
Molecular function: olfactory receptor activity; G protein-coupled receptor activity; odorant binding
Biological process: detection of chemical stimulus involved in sensory perception of smell; detection of chemical stimulus involved in sensory perception; G protein-coupled receptor signaling pathway
Cellular component: plasma membrane; cell cortex; membrane
Genetic constraint (gnomAD): Loss-of-function variants: 2 observed, 0.5 expected, observed/expected ratio (o/e) 3.99. That is too few expected variants to judge how well the gene tolerates losing a copy. Missense variants: 468 observed, 404.28 expected, observed/expected ratio (o/e) 1.16, 90% interval 1.07 to 1.25. Synonymous variants: 209 observed, 174.79 expected, observed/expected ratio (o/e) 1.2, 90% interval 1.07 to 1.34.
Homologues: Orthologues: dog OR2C1 (87% identical), rabbit OR2C1 (85% identical), pig OR2C1 (84% identical), guinea pig OR2C1 (84% identical), rat Or2c1 (83% identical), mouse Or2c1 (82% identical). Paralogues in human: OR2G3 (59% identical), OR2H2 (59% identical), OR2H1 (58% identical), OR2C3 (57% identical), OR2G6 (56% identical), OR2G2 (56% identical), OR2W3 (56% identical), OR2Y1 (56% identical), OR2B2 (55% identical), OR2B6 (55% identical), OR2J3 (54% identical), OR2J2 (54% identical), and 80 more.
Diseases named in the same sentence as OR2C1 in open-access papers:
OR2C1 is named in the same sentence as 2 diseases in open-access papers, as found by Europe PMC text mining. Sharing a sentence is not in itself a finding about the gene and the disease. The quoted sentences say what the papers report.
glioma (1 paper, 2023). A benign or malignant brain and spinal cord tumor that arises from glial cells (astrocytes, oligodendrocytes, ependymal cells). "Limited reports have found that OR2C1 favor the survival of isocitrate dehydrogenase wild-type glioma, certifying that OR2C1 was one of the therapeutic targets for glioma." (PMID 36675176, 2023).
vitiligo (1 paper, 2021). Generalized well circumscribed patches of leukoderma that are generally distributed over symmetric body locations and is due to autoimmune destruction of melanocytes. "In total, we propose the genes NUBPL, PHF11, SETDB2, RCBTB1, PTP4A1, and at a weaker replication level the genes LITAFD, CARHSP1 and OR2C1 as possible candidates for vitiligo-like depigmentation in grey horses." (PMID 34696794, 2021).